GPR65 (G protein-coupled receptor 65)
Description:
Proton-sensing G protein-coupled receptor activated by extracellular pH, which is required to monitor pH changes and generate adaptive reactions. Activated by an optimal pH of 7.4. Ligand binding causes a conformation change that triggers signaling via guanine nucleotide-binding proteins (G proteins) and modulates the activity of downstream effectors, such as adenylate cyclase. GPR65 is mainly coupled to G(s) G proteins and mediates activation of adenylate cyclase activity. May also act as a receptor for the glycosphingolipid psychosine (PSY) and several related glycosphingolipids. Plays a role in immune response by maintaining lysosome function and regulating T-cell metabolism. Acts as a regulator of inflammation by mediating pH-sensing of extracellular acidification which takes place in inflamed tissues: activation regulates endo-lysosomal function of immune cells and T-cell metabolism (By similarity). Constitutively active in endosomes and stimulates adenylate cyclase production from endosomes independently from extracellular pH changes.
Synonyms: TDAG8; hTDAG8
Tractability: Small molecule: it belongs to a druggable protein family. Antibody: UniProt places it where antibodies can reach, with high confidence; its Gene Ontology location is reachable by antibodies, with high confidence; UniProt predicts a signal peptide or a membrane-spanning region. PROTAC: a small molecule that binds it is known.
Target class: Family A G protein-coupled receptor; Membrane receptor
Gene: Protein-coding gene on chromosome 14 (88,005,135 to 88,014,811, forward strand). Ensembl gene ENSG00000140030.
Subcellular location: Cell membrane; Early endosome membrane; Late endosome membrane
Subcellular location (Human Protein Atlas): Vesicles; Cytosol; Nucleoli
Pathways (Reactome):
Signal Transduction: Class A/1 (Rhodopsin-like receptors); G alpha (q) signalling events
Gene Ontology:
Molecular function: G protein-coupled receptor activity
Biological process: adenylate cyclase-activating G protein-coupled receptor signaling pathway; cellular response to acidic pH; G protein-coupled receptor signaling pathway; positive regulation of stress fiber assembly; response to acidic pH; immune response; positive regulation of interleukin-22 production; positive regulation of T-helper cell differentiation
Cellular component: early endosome membrane; late endosome membrane; plasma membrane; membrane
Genetic constraint (gnomAD): Loss-of-function variants: 5 observed, 3.28 expected, observed/expected ratio (o/e) 1.52, 90% interval 0.71 to 1.93. That is too few expected variants to judge how well the gene tolerates losing a copy. Missense variants: 308 observed, 333.86 expected, observed/expected ratio (o/e) 0.92, 90% interval 0.84 to 1.01. Synonymous variants: 97 observed, 120.26 expected, observed/expected ratio (o/e) 0.81, 90% interval 0.68 to 0.95.
Homologues: Orthologues: chimpanzee GPR65 (99% identical), macaque GPR65 (96% identical), rabbit GPR65 (84% identical), pig GPR65 (82% identical), guinea pig GPR65 (81% identical), rat Gpr65 (80% identical), mouse Gpr65 (79% identical), dog GPR65 (57% identical), tropical clawed frog gpr65 (43% identical), zebrafish gpr65 (32% identical), Caenorhabditis elegans gnrr-4 (22% identical). Paralogues in human: GPR4 (39% identical), F2RL1 (27% identical), LPAR4 (27% identical), LPAR6 (26% identical), F2R (24% identical), F2RL3 (24% identical), GPR17 (23% identical), P2RY8 (23% identical), P2RY10 (23% identical), CYSLTR2 (23% identical), CYSLTR1 (22% identical), F2RL2 (22% identical), and 4 more.
Diseases named in the same sentence as GPR65 in open-access papers:
GPR65 is named in the same sentence as 108 diseases in open-access papers, as found by Europe PMC text mining. Sharing a sentence is not in itself a finding about the gene and the disease. The quoted sentences say what the papers report.
ovarian carcinoma (27 papers, 2013 to 2025). A malignant neoplasm originating from the surface ovarian epithelium. "This includes G-protein receptor 4 (GPR4), T cell death-associated gene 8 (TDAC8, or GPR65), and ovarian cancer G-protein coupled receptor 1 (OGR1, or GPR68)." (PMID 41091845, 2025). "pHRs are class A GPCRs that consist of three members, G protein coupled receptor 4 (GPR4), T cell death-associated gene 8 (TDAG8, aka GPR65) and ovarian cancer G-protein coupled receptor 1 (OGR1, aka GPR68)." (PMID 38340167, 2024). "This subfamily of proteins is composed of four members: G protein-coupled receptor 4 (GPR4 or Gpr4), T-cell death–associated gene 8 (TDAG8 or Gpr65), ovarian cancer G protein–coupled receptor 1 (OGR1 or Gpr68), and G protein–coupled receptor 132 (G2A or Gpr132)." (PMID 35247105, 2022). "Proton-sensing GPCRs—notably GPR4, GPR65 (also known as T-cell death-associated gene 8, TDAG8), and GPR68 (also known as ovarian cancer G-protein-coupled receptor 1, OGR1)—are transmembrane receptors that detect extracellular acidification." (PMID 41375084, 2025). "G-protein-coupled receptors (GPRs), including pro-inflammatory ovarian cancer GPR1 (OGR1/GPR68) and anti-inflammatory T cell death-associated gene 8 (TDAG8/GPR65), are involved in pH sensing and linked to inflammatory bowel disease (IBD)." (PMID 37834303, 2023). "The family includes T-cell death-associated gene 8 (TDAG8 or GPR65), ovarian cancer G-protein coupled receptor 1 (OGR1 or GPR68), G2 accumulating protein (G2A or GPR132), and GPR4." (PMID 36233248, 2022). "A family of G protein-coupled receptors (GPCRs): including ovarian cancer G-protein coupled receptor 1 (OGR1, also known as GPR68), GPR4 and T-cell death associated gene 8 (TDAG8, also known as GPR65), are activated by acidic extracellular pH." (PMID 31996710, 2020). "The family of proton-sensing GPCRs include four members: GPR4, GPR65, or T-cell death-associated gene 8 (TDAG8), GPR68, or Ovarian cancer G protein-coupled receptor 1 (OGR1) and GPR132 or G2A." (PMID 33113952, 2020). "It belongs to a small G protein-coupled proton-sensing receptor family that includes ovarian cancer G protein-coupled receptor 1 (OGR1), also referred to as GPR68, G2A, also termed GPR132, and T-cell death-associated gene 8 (TDAG8), also known as GPR65." (PMID 33053856, 2020). "There are four members within this family of receptors, the Ovarian Cancer G-Protein Coupled Receptor Protein1 (OGR1, GPR68), G-protein Coupled Receptor 4 (GPR4), G2 accumulation (G2A, GPR132), and T Cell Death-Associated Gene 8 (TDAG8, GPR65)." (PMID 36010617, 2022). "The family of GPCR includes the ovarian cancer G protein-coupled receptor 1 (OGR1, also known as GPR68), the G protein-coupled receptor 4 (GPR4), the T cell death-associated G protein 8 (TDAG8, also known as GPR65), and the G2 accumulation protein (G2A, also known as GPR132)." (PMID 30825056, 2019). "In response to acidic extracellular pH, GPR65 induces an anti-inflammatory response, whereas the two other proton-sensing receptors, GPR4 and GPR68 (ovarian cancer G protein-coupled receptor 1, OGR1), mediate pro-inflammatory responses." (PMID 38514581, 2024). "In agreement with data suggesting significant and strong co-expression of CX3CR1 with GPR65 and FFAR4 in specimens, western blot confirmed robust downregulation of GPR65 and FFAR4 in ovarian carcinoma cell lines transfected with CX3CR1-specific siRNAs." (PMID 29712888, 2018).
colitis (17 papers, 2019 to 2025). Inflammation of the colon. "GPR65 polymorphism with a substitution of isoleucine to leucine at codon 231 was identified as a risk factor in colitis." (PMID 39336742, 2024). "Although inhibition of pH-sensing family members GPR4 and GPR68 has been reported to improve outcomes in murine colitis models, only GPR65 has annotated genetic variants that correlate with IBD." (PMID 39028811, 2024). "Deletion of Tdag8 in mice or knock-in of the IBD-associated variant GPR65 I231L results in lysosomal dysfunction, which impacts bacterial autophagy and pathogen defense, thereby increasing the risk of developing colitis." (PMID 38514581, 2024). "Expression of GPR65 has been shown to be critical for innate host defense, and loss of GPR65 exacerbates inflammatory pathology in Citrobacter rodentium and T cell transfer models of colitis." (PMID 39028811, 2024). "GPR65 deficiency aggravated intestinal inflammation and promoted colitis-associated colorectal cancer development in IBD mouse models." (PMID 39336742, 2024). "Ile231Leu-GPR65 knock-in mice were challenged with bacteria and T-cell-mediated colitis and showed increased susceptibility to colitis." (PMID 39336742, 2024). "Upregulated GPR65 suppresses intestinal inflammation and reduces the risk of developing colitis-associated colorectal cancer in an experimental mouse model." (PMID 36902589, 2023). "Given that epithelial cell-derived GPR65 is associated with intestinal antimicrobial defense, we sought to determine its role in the development of colitis." (PMID 37749885, 2023). "As expected, selective depletion of GPR65 in IECs predisposes mice to colitis triggered by DSS and C. rodentium infection." (PMID 37749885, 2023). "Another study found that GPR65 can inhibit intestinal inflammation and colitis‐associated colorectal cancer development." (PMID 35343079, 2022). "Moreover, the progression of DSS-induced colitis is aggravated by GPR65 deficiency, which supports the protective role of GPR65 in this model." (PMID 38274786, 2023). "Furthermore, the IBD susceptibility gene GPR65 (coding for the G protein-coupled receptor 65, an H+-sensing G protein-coupled receptor) plays a role in maintaining the lysosomal function, preserving autophagy and colitis risk." (PMID 37240022, 2023). "We then investigated the association between GPR65 expression and colitis in mouse models." (PMID 37749885, 2023). "Therefore, potentiating GPR65 activity with agonists or PAMs may reduce risk of developing colitis-associated colorectal cancer." (PMID 39028811, 2024). "Rag1−/− mice reconstituted with GPR65 I231L or GPR65 knockout (KO) CD4+ T cells demonstrate more severe colitis phenotypes compared to those reconstituted with GPR65 wild-type (WT) CD4+ T cells." (PMID 39028811, 2024). "Overall, these studies demonstrate through various mechanisms that there is an inverse correlation between GPR65 expression and colitis severity." (PMID 39336742, 2024). "Collectively, these data confirm a protective effect of epithelial GPR65 on intestinal mucosal inflammation in a bacterium-driven colitis model." (PMID 37749885, 2023). "We found a decrease in GPR65 expression in IECs from IBD patients and colitis mice, pointing to an important role for epithelial GPR65 in colitis development and progression." (PMID 37749885, 2023). "For this purpose, we isolated colonic epithelial cells from both DSS-induced colitis mice and control mice and found that the protein levels of GPR65 were markedly downregulated in IECs from colitis mice." (PMID 37749885, 2023). "We next dissected the potential mechanisms whereby Gpr65 confines colitis and regulates the differentiation of CD4+ T cell." (PMID 35343079, 2022). "Mice with IEC-specific GPR65 deletion exhibited dysbiosis of fecal microbiota and enhanced susceptibility to both dextran sulfate sodium (DSS)- and C. rodentium infection-induced colitis." (PMID 37749885, 2023).
colitis (continued). "Experimentally induced colitis in GPR65 global knockout mice resulted in an exacerbated disease phenotype compared to control mice, which led investigators to conclude that epithelial cells and macrophages lacking GPR65 caused lysosomal dysfunction and promoted intestinal inflammation." (PMID 35678010, 2022). "The absence of GPR65 in IECs causes a diminishment in antimicrobial defense and subsequent dysbiosis, which is responsible for the disrupted barrier integrity and enhanced susceptibility to colitis." (PMID 37749885, 2023). "Besides, mice lacking Gpr65 have increased susceptibility to Citrobacter rodentium‐induced colitis, and epithelial cells (HeLa cells) and macrophages lacking GPR65 exhibit flawed intracellular bacterial clearance and anomalous lysosomes assemblage." (PMID 35343079, 2022). "Herein we generated mice with IEC-specific deletion of Gpr65 (Gpr65ΔIEC) and investigated the role of epithelial GPR65 using DSS- and C. rodentium-induced murine colitis models." (PMID 37749885, 2023). "The expression of GPR65 was determined in IECs from patients with inflammatory bowel disease (IBD) and DSS colitis mice by qRT-PCR, Western blot, and immunohistochemistry, respectively." (PMID 37749885, 2023). "Moreover, conditional knockout of GPR65 in CD4+ T cells reduced Th1 and Th17 cell immune responses in colon mucosa and alleviated intestinal inflammation in murine colitis models." (PMID 39336742, 2024). "In addition, a reduced expression of GPR65 in intestinal epithelial cells in mice aggravated DSS- and C. rodentium-induced colitis through the disruption of epithelial antimicrobial responses." (PMID 39336742, 2024). "Finally, the expression of GPR65 was markedly decreased in the inflamed epithelia of IBD patients and DSS colitis mice." (PMID 37749885, 2023). "Nevertheless, the potential function of GPR65 in regulating mucosal CD4+ T cell functions during colitis and maintaining intestinal homeostasis remains not fully understood." (PMID 35343079, 2022). "But other researches demonstrated that the lack of GPR65 in macrophages and epithelial cells exhibits a detrimental role in colitis due to lysosomal dysfunction and impaired clearance of intracellular bacteria." (PMID 35343079, 2022). "Finally, we found a decrease in GPR65 in the inflamed epithelia of IBD patients and DSS colitis mice, highlighting that dysregulated GPR65 signaling in IECs could exacerbate the development of intestinal inflammation." (PMID 37749885, 2023). "To clarify whether GPR65 modulates mucosal CD4+ T cell immune responses and promotes the development of colitis, we constructed mice with CD4+ T cell‐specific knockout of Gpr65 gene (Gpr65ΔCD4 mice) and investigated the potential role of GPR65 in modulating CD4+ T cell activation during colitis." (PMID 35343079, 2022). "Here, we unravelled that the expression of GPR65 was enhanced in inflamed gut mucosa and PB‐CD4+ T cells of active IBD patients and identified that GPR65 could facilitate Th1 and Th17 cell differentiation and participate in the etiopathogenesis of colitis by impeding NUAK2 expression." (PMID 35343079, 2022).
inflammatory bowel disease (12 papers, 2019 to 2026). A spectrum of small and large bowel inflammatory diseases of unknown etiology. "GWAS have identified numerous variants in the GPR65 locus that are in linkage disequilibrium with each other and associated with multiple sclerosis and inflammatory bowel disease (IBD)." (PMID 39028811, 2024). "Genome-wide association studies linked GPR65 to several autoimmune and inflammatory diseases such as multiple sclerosis and inflammatory bowel disease (IBD)." (PMID 39028811, 2024). "G protein‐coupled receptor 65 (GPR65), a susceptibility gene for inflammatory bowel diseases (IBD), has been identified to promote Th17 cell pathogenicity and induce T cell apoptosis." (PMID 35343079, 2022). "For example, a genetic variant of TDAG8 (GPR65) that leads to amino acid exchange and reduces activity and signaling of the receptor has been associated with alterations in lysosomal pH and lysosomal dysfunction in the pathophysiological context of inflammatory bowel disease." (PMID 34440817, 2021). "Numerous genome wide association studies (GWAS) linking GPR65 polymorphism to increased incidence of inflammatory bowel disease (IBD) and other autoimmune/autoinflammatory diseases highlight the importance of GPR65’s regulatory functions on the immune system." (PMID 39483470, 2024). "GPR4 and GPR65 have both been attributed functions in inflammatory bowel disease (IBD)." (PMID 38374228, 2024).
lymphoma (10 papers, 2013 to 2024). A malignant (clonal) proliferation of B- lymphocytes or T- lymphocytes which involves the lymph nodes, bone marrow and/or extranodal sites. "Alternatively, GPR65 gene expression promotes glucocorticoid-induced apoptosis in murine lymphoma cells as well as reducing c-myc oncogene expression in human lymphoma cells." (PMID 39336742, 2024). "For example, the expression of GPR65 in human lymphoma samples is significantly reduced compared with that in normal lymphoid tissues, indicating that GPR65 has a potential tumor suppressor function in lymphoma." (PMID 37723567, 2023). "In summary, this study reveals that the acid-sensing receptor TDAG8 (GPR65) is down-regulated in multiple types of hematological malignancies, including leukemia, lymphoma and multiple myeloma." (PMID 29017562, 2017). "Acidosis activation of GPR65 has been reported to reduce c-Myc expression in lymphoma and leukemia cells." (PMID 25988385, 2015). "According to the Oncomine database and a recent publication, GPR65 expression is reduced in lymphoma and leukemia samples when compared to normal lymphoid tissues." (PMID 25988385, 2015). "An overexpression of GPR65 promotes glucocorticoid-induced apoptosis in mouse lymphoma cells." (PMID 36902589, 2023). "However, other experiments performed in the same murine lymphoma cell line (WEHI7.2) show that GPR65 overexpression induces apoptosis while its silencing prevents the pro-apoptotic effect of glucocorticoids." (PMID 33113952, 2020). "GPR65 has also been shown to enhance corticosteroids-induced lymphoma cell apoptosis." (PMID 25988385, 2015). "Furthermore, bioinformatic analysis of the Oncomine microarray database revealed that the expression of TDAG8 (GPR65) was significantly lower (2.021 fold decrease, p < 0.001) in follicular lymphoma when compared to normal lymphocytes, concordant with the real-time RT-PCR results of lymphoma samples." (PMID 24152439, 2013).
Arthritis (7 papers, 2013 to 2024). Inflammation of a joint. "GPR65 deficiency also exacerbates disease in collagen antibody-induced arthritis models, yet loss of GPR65-expressing CD4+ T cells protects against autoimmune encephalomyelitis in Rag1−/− mice." (PMID 39028811, 2024). "Furthermore, GPR65 knockout (KO) mice exhibit reduced pain behaviors following localized injection of acid, or induction of experimental arthritis, which has been linked to reduced infiltration of immune cells." (PMID 39661058, 2024).
lung carcinoma (6 papers, 2013 to 2025). "Increased levels of GPR65 were associated with the growth of lung cancer cells and the transformation of mammary epithelial cells." (PMID 36046070, 2020). "We found that knockdown of GPR65 in lung cancer cells significantly increased the proliferation of A549 and H1299 compared to the control (Vector)." (PMID 40519919, 2025). "GPR65 was reported to facilitates lung cancer development via PKA/ERK pathway by serving as an extracellular pH sensor." (PMID 38576043, 2024). "In addition, they performed additional bioinformatics analysis of the tumor database and found an interesting phenomenon: GPR65 expression was either unaltered or downregulated in lung cancer samples compared to normal lung tissue." (PMID 40519919, 2025). "In a murine model, overexpression of GPR65 increased tumour growth via a mechanism that may involve adaptation to acidic conditions through activation of PKA and ERK; knockdown of this receptor inhibited survival of lung cancer cells in an acidic environment." (PMID 36046070, 2020).
rheumatoid arthritis (5 papers, 2017 to 2024). A chronic, systemic autoimmune disorder characterized by inflammation in the synovial membranes and articular surfaces. "In a rheumatoid arthritis (RA) mouse model, GPR65 deficiency reduced hyperalgesia and RA score and significantly decreased IL-6 and IL-17 production." (PMID 39336742, 2024).